BRAF (B-Raf proto-oncogene, serine/threonine kinase)
Diseases named in the same sentence as BRAF in open-access papers (continued):
Sharing a sentence is not in itself a finding about the gene and the disease.
epilepsy (18 papers, 2018 to 2025). A brain disorder characterized by episodes of abnormally increased neuronal discharge resulting in transient episodes of sensory or motor neurological dysfunction, or psychic dysfunction. "Three of the 25 patients presented with BRAF V600E mutations (one of 10 in the drug-responsive epilepsy group and 2 of 15 in the DRE group)." (PMID 40103938, 2025). "CNTNAP2 has previously been linked to autism and intellectual disability, BRAF to epilepsy, TRANK1 to schizophrenia, and LRPPRC/MYO7A to mitochondrial and ciliary disorders." (PMID 40282380, 2025). "In the most common genotype with BRAF variants, a genotype-phenotype correlation has been reported between the structure and function of variants and the severity of epilepsy." (PMID 39086472, 2024). "The results indicated that pulmonary valve stenosis, curly/sparse hair, and epilepsy were less likely to occur in Chinese CFC patients with BRAF variants, whereas curly/sparse hair and hypotonia were rare in Chinese patients with MAP2K1/2 variants." (PMID 37697378, 2023). "The study found that while CD34 expression was significantly associated with a longer duration of epilepsy, BRAF mutation was associated with multiple seizure types." (PMID 36894761, 2023). "Several of the cerebellar specific protein alterations are associated with neurological diseases including epilepsy and intellectual disability including BRAF, CRMP5 and ASNS." (PMID 35264729, 2022). "The study found that while CD34 expression (59.1% of cases) was significantly associated with a longer duration of epilepsy (median duration of 16 years), BRAF mutation (50% of cases) was associated with multiple seizure types." (PMID 29701169, 2018). "The BRAF mutation is associated with various types of epilepsy." (PMID 39634774, 2024). "Even so, our results could partly complement the undefined domains of the clinicopathological features of molecular alterations (CD34 and BRAF mutation) in GG with epilepsy, as well as the long-term surgical outcomes." (PMID 36910263, 2023). "The clinical significance of CD34 expression and BRAF mutation was investigated in a recent publication aiming to study the relationship between biomolecular markers and clinical-pathological features in 22 cases of low-grade epilepsy-associated neuroepithelial tumors." (PMID 29701169, 2018). "Some groups thus separate epilepsy-associated tumors into those with FGFR1 mutations (DNTs) and those with BRAF mutations." (PMID 37525202, 2023). "Epilepsy represents a major clinical issue in CFCS, a developmental disorder caused by activating de novo BRAF mutations." (PMID 34573299, 2021). "While the presence of BRAF V600E mutations can influence the age of epilepsy onset, it does not appear to impact postsurgical outcomes." (PMID 38846038, 2024). "Second, other factors related to the prognosis of epilepsy-associated tumors were not considered, such as BRAF V600E mutation rate and CD34 positivity rate." (PMID 36672006, 2022).
hyperplastic polyp (18 papers, 2006 to 2022). A polyp found mainly in the stomach and colon. "All serrated polyps (hyperplastic polyps or sessile serrated adenoma/polyps) were KRAS or BRAF-mutated, mostly the latter (70.6%, n = 12/17)." (PMID 32517177, 2020). "In the multivariate analyses, the presence of serrated histology and hyperplastic polyps remained significantly and independently associated with BRAF V600E mutations (OR, 20.6; 95% CI, 8.2-51.8 and OR, 11.9; 95% CI 4.9-29.0, respectively)." (PMID 26910894, 2016). "A strong association was found between BRAF mutations and both serrated adenomas and hyperplastic polyps during multivariate analysis." (PMID 26910894, 2016). "The BRAF mutation rates in serrated adenomas and hyperplastic polyps were lower than that reported in previous studies." (PMID 26910894, 2016). "Of the 77 BRAF V600E mutations, 64.9% (50/77) present in serrated lesions (50.0% in serrated adenomas and 36.9% in hyperplastic polyps)." (PMID 26910894, 2016). "Once thought to lack potential for malignant progression, hyperplastic polyps are now considered to represent a heterogeneous group, most of which harbor BRAF mutations and some of which exhibit epigenetic alterations (both uncommon in colorectal adenomas)." (PMID 21559209, 2011). "Several studies have shown a variety of genetic changes within these hyperplastic polyps, including increased frequency of chromosomal 1p allelic loss, somatic BRAF (80% of HP’s) and k-RAS2 (10% of HP’s) mutations." (PMID 19424478, 2008). "BRAF mutation has been shown to be a specific marker for a serrated polyp pathway that has its origin in a hyperplastic polyp and a potential end point as MSI carcinoma." (PMID 18718023, 2008). "Both MSI+ and CIMP+ tumors are thought to arise from large hyperplastic polyps and serrated adenomas and recent work has demonstrated a high frequency of BRAF mutations in these lesions." (PMID 16403224, 2006). "Microvesicular hyperplastic polyp subtype may present mutation in BRAF oncogene suggesting this type of injury as a precursor serrated adenoma that can be a CRC precursor." (PMID 31653137, 2019). "We found 20 KRAS mutations and 24 BRAF mutations in these 65 hyperplastic polyps." (PMID 26910894, 2016). "It has been proposed that a hyperplastic polyp (HP) is initiated by a BRAF mutation." (PMID 23671423, 2013). "Although we observed a higher frequency in BRAF when comparing hyperplastic polyps and SSL, this difference was not significant when adjusted analysis were performed." (PMID 35761395, 2022). "BRAF mutation is likely to be a convenient marker for the identification of a subset of CRCs with distinctive clinical, pathological and molecular features which may originate in hyperplastic polyps and serrated adenomas, while increases the risk of mortality in CRC patients by more than two-fold." (PMID 25361007, 2014). "Findings from the present study and from previous work indicate that BRAF mutation is likely to be a convenient marker for the identification of a subset of CRCs with distinctive clinical, pathological and molecular features and which may originate in hyperplastic polyps and serrated adenomas." (PMID 16403224, 2006). "In contrast to BRAF mutations, KRAS mutations were comparatively infrequent in serrated crypt foci (3/16), absent in dysplastic serrated adenoma (0/9), but present in 9/50 hyperplastic polyps." (PMID 26299805, 2015). "We found that 60% of SSA/Ps had V600E mutations in BRAF while no mutations were observed in hyperplastic polyps and controls." (PMID 24533081, 2014). "Evidence also suggests that cigarette smoking (related to CIMP and BRAF) may be associated with hyperplastic polyps rather than adenomatous polyps; a subset of hyperplastic polyps has been hypothesized to be the precursor to CIMP high colorectal carcinomas." (PMID 21559209, 2011).
hyperplastic polyp (continued). "BRAF cDNA from syndromic SSA/Ps, hyperplastic polyps (HPs) and normal colon was amplified by PCR and sequenced since T to A mutations in codon 600 resulting in a valine to glutamic acid (V600E) amino acid change with increased kinase activity have been reported in SSA/Ps." (PMID 24533081, 2014).
oligodendroglioma (17 papers, 2017 to 2025). A well-differentiated (WHO grade II), diffusely infiltrating neuroglial tumor, typically located in the cerebral hemispheres. "Recent investigations have unveiled a unique subset of tumors within this category, characterized by their IDH wildtype status, oligodendroglioma-like morphology, and BRAF p.V600E mutation." (PMID 39227895, 2024). "Understanding the pathophysiology of BRAF V660E mutant oligodendrogliomas within the context of CIN and molecular genetics is paramount for informed clinical decision-making." (PMID 39227895, 2024). "CIN is central in deciphering the intricate pathophysiology of BRAF V660E mutant oligodendrogliomas, especially in adolescents and children." (PMID 39227895, 2024). "In fact, the diagnosis of PLNTY relies on the following essential criteria: “diffuse growth pattern and oligodendroglioma-like component and few (if any) mitotic figures and regional CD34 expression and IDH-wild type status and BRAF V600E mutation or FGFR2 or 3 fusions”." (PMID 36647073, 2023). "The PDGFb model mimics transforming oligodendrogliomas in AYA patients, while the BRAF V600E model reflects transforming xanthoastrocytoma in pediatric patients." (PMID 40527978, 2025).
bladder cancer (16 papers, 2011 to 2025). "The aim of this study was to test the efficacy of AI histology to predict the presence of the BRAF mutation in canine bladder carcinomas and to assess its intratumoral heterogeneity." (PMID 37570213, 2023). "In recent years, it has been shown that the V595E mutation in BRAF, the canine homolog to human BRAF V600E, occurs in up to 87% of canine urinary bladder carcinomas, and known high-risk dog breeds are particularly frequently affected." (PMID 37570213, 2023). "The mutations also appear more random, lacking a prominent mutated gene like ERBB2 in pulmonary cancer and BRAF in bladder cancer." (PMID 37414794, 2023). "Despite these reports, the only clinical trial that utilizes MEK inhibition in bladder cancer is the ongoing MATCH screening trial in advanced solid tumors (NCT02465060), using mutation status of BRAF, GNA11, and NF1 to identify potential responders to the MEK inhibitor, Trametinib." (PMID 33216841, 2020). "The KEGG bladder cancer pathway activation in poor prognosis CRCs was mostly due to increased expression of functional nodes HRAS/KRAS/NRAS, ARAF/BRAF/RAF1, MAPK1/MAPK3, and RPS6KA5." (PMID 36316649, 2022).
neurofibromatosis type 1 (16 papers, 2011 to 2025). A clinically heterogeneous, neurocutaneous genetic disorder characterized by cafe-au-lait spots, iris Lisch nodules, axillary and inguinal freckling, and multiple neurofibromas. "The tumorigenesis is related to alteration in MAPK pathway, commonly as BRAF fusion or BRAF V600E point mutation, and can also be seen in association with neurofibromatosis-type 1." (PMID 35454009, 2022). "A favorable outcome is seen in patients with BRAF fusion and neurofibromatosis type 1, while those with the BRAF V600E show a high risk of progression and transformation." (PMID 34676470, 2021). "This group is heterogeneous, not typically responsive to imatinib or other typical tyrosine kinase inhibitors (TKI), and includes SDH-deficient tumors (14%), tumors with mutations in NF1 (type 1 neurofibromatosis), BRAF V600E, and NTRK (0.5% each), and other rare mutations." (PMID 35954353, 2022). "Allosteric MEK1 inhibitors are used in combination with B-RAF inhibitors for treating BRAF V600-mutant cancers or as monotherapies for neurofibromatosis type I." (PMID 41199836, 2025). "WT-GISTs have other genetic alterations, including mutations of the succinate dehydrogenase and serine–threonine protein kinase BRAF and neurofibromatosis type 1." (PMID 39176108, 2024). "Besides the mutations on BRAF/RAS, it has been reported that the autosomal-dominant inherited disease, neurofibromatosis Type 1 (NF1), promotes an increased incidence of GIST." (PMID 35582147, 2019). "One patient had neurofibromatosis type I. BRAF status was unknown for these patients at inclusion." (PMID 30319400, 2018). "Seven genes (PTPN11, SOS1,KRAS, RAF1, BRAF,SHOC2 and MEK1, alias MAP2K1) have beencausally related to NS and closely related conditions (including LEOPARDsyndrome) and clinically related disorders (e.g. neurofibromatosis type 1)." (PMID 21526175, 2011).
Obesity (16 papers, 2014 to 2026). Accumulation of substantial excess body fat. "BRAF V600E accounts for 60% of all TC mutations, and the prevalence of obesity is significantly related to the BRAF V600E mutation in TC." (PMID 35032114, 2022). "The link between obesity and the BRAF V600E mutation in TC theoretically establishes a pathophysiological mechanism for obesity‐induced TC." (PMID 35032114, 2022). "The findings from the present study demonstrate a significant association of obesity with BRAF wild type tumours, being particularly evident in men." (PMID 24918610, 2014). "Likewise, in PTC, patients with obesity harbored a higher prevalence of BRAF mutations compared to over- and normal-weight ones." (PMID 40149286, 2025). "Despite the known risk factors for PTC including radiation exposure, iodine uptake, obesity, and the deep research on the molecular etiology of BRAF, RAS, and RET mutations, the mechanism of the incidence and development of PTC is still unknown." (PMID 36612238, 2022). "Obesity, a sedentary lifestyle, alcohol, processed meats, a red-meat-rich diet, and smoking are all factors found in developed countries that increase the risk of developing BRAF gene mutation and having CRC." (PMID 36277559, 2022). "Since KRAS and BRAF mutations are thought to occur early in colorectal carcinogenesis, it seems biologically plausible that exposures such as obesity might modulate CRC risk differentially according to KRAS and BRAF mutation status of the tumours." (PMID 24918610, 2014). "They concluded that the greater risk of BRAF-mutated PTCs among those with high BMI suggests that the association may not merely reflect greater health care service use and indicates an independent relationship between obesity and clinically relevant TC." (PMID 33801171, 2021). "Moreover, accumulation of DNA mutations, such as APC, KRAS, NRAS, BRAF, or PIK3CA, makes obesity a multifactor phenomenon involved in CRC initiation and progression." (PMID 36235624, 2022). "Moreover, accumulation of DNA mutations, as in APC, KRAS, NRAS, BRAF, or PIK3CA, and insulin secretion sets obesity as a multifactor phenomenon involved in CRC initiation and aggressive development." (PMID 26801617, 2016). "In this prospective cohort study, we have investigated the relationship between obesity, measured as several anthropometric factors, and risk of CRC according to KRAS and BRAF mutation status of the tumours, with particular reference to potential sex differences." (PMID 24918610, 2014). "Hence, the aim of this prospective cohort study was to investigate the associations of obesity, measured as several anthropometric factors, with CRC risk according to KRAS and BRAF mutation status of the tumours, overall, and with particular reference to potential sex differences." (PMID 24918610, 2014). "This suggests that obesity is more related to MSS tumours, and to tumours lacking BRAF mutation." (PMID 24918610, 2014).
malignant glioma (15 papers, 2014 to 2024). A grade III or grade IV glioma arising from the central nervous system. "In a study involving the combination of dabrafenib and trametinib for recurrent or refractory high-grade gliomas (HGG) with the BRAF V600E mutation, an objective response was observed in 32% of GBM patients, with a complete response in 6.5% of cases." (PMID 39484048, 2024). "In the pediatric population, BRAF V600E mutations are commonly found in low-grade gliomas (LGGs) and approximately 6–10% of high-grade gliomas (HGGs)." (PMID 34965294, 2021). "We propose that BRAF mutation should be tested routinely for GBMs and the other malignant gliomas during the histopathological assay." (PMID 33117675, 2020). "In a large cohort study of CNS tumors ranging from grade I to grade IV cancers, BRAF V600E mutation occurred most frequently in 66.7% of PXAs, but was also found at lower levels in PAs, GGs, and malignant gliomas." (PMID 25785246, 2015). "The KIAA1549:BRAF fusion has been reported in a range of PAs (59–90%) and so it is increasingly used as a diagnostic marker for PAs, where neuropathological distinction from malignant glioma can be difficult." (PMID 25785246, 2015). "With the advent of inhibitors of MEK and BRAF, targeted therapeutic options have been shown in clinical trials to have a role in relapsed/refractory pLGG and paediatric high grade glioma (pHGG)." (PMID 34493325, 2021). "Oncogenic BRAF mutation and CDKN2A inactivation characterize a subset of pediatric malignant gliomas." (PMID 29152094, 2017). "The stark difference in the posthoc survival analysis of tumor-bearing BRAF-KD and BRAF-FLVE mice (P<0.001) as well as the lower level of P-Erk1 and P-Erk2 (P<0.001) in astrocytes expressing BRAF-KD compared to BRAF-FLVE suggests that the BRAF-KD tumors are less malignant gliomas." (PMID 25821557, 2015). "Patients 11–15 had BRAF-altered malignant gliomas or PXAs and were treated with a BRAF inhibitor with or without a MEK inhibitor." (PMID 35864412, 2022). "Although not clear yet, these diverse responses are likely related to the complex genetic aberrations present in malignant gliomas which might induce the overactivation of MAP kinase through alternative pathways, regardless of the BRAF status, and thus impair the efficacy of the treatment." (PMID 25524464, 2014).
medullary thyroid cancer (15 papers, 2013 to 2025). "The BRAF mutation has been detected in 45% of papillary thyroid carcinoma (PTC) and in 24% of atypical subtype, whereas the mutation has not been detected in follicular and medullary thyroid carcinoma (FTC and MTC, respectively)." (PMID 29061943, 2015).